IFITM3 (interferon induced transmembrane protein 3)
Diseases named in the same sentence as IFITM3 in open-access papers (continued):
Sharing a sentence is not in itself a finding about the gene and the disease.
infection (continued). "We could also confirm that IFITM3 knockdown significantly increased the infection rates of HuH7-NTCP cells for IAV, confirming that our HuH7-NTCP cell clone is reactive in the manner reported in the literature." (PMID 35458456, 2022). "This represents the first evidence that IFITM3 can restrict the infection of RV." (PMID 36366505, 2022). "At the same time, IFITM3 significantly increased after infection for 36 h." (PMID 36366505, 2022). "Our observations suggested colocalization (yellow) between TLR2 and Nogo-B after HCMV exposure; and that TLR2 and Nogo-B cellular localisation was influenced by IFITM3, with more TLR2/Nogo-B localisation visible as cytoplasmic puncta in IFITM3−/− iPS-DCs 24 h post infection." (PMID 36075894, 2022). "To decouple lung inflammation and the direct infection of cardiomyocytes that both occur in IFITM3 KO mice, we designed, rescued, and validated a recombinant influenza virus that is attenuated for replication in cardiomyocytes while being fully replication competent and inflammatory in the lungs." (PMID 35544568, 2022). "Similarly, all WT mice recovered from infections with either virus strain, while both infections were lethal in IFITM3 KO mice." (PMID 35544568, 2022). "Importantly, increased IFITM3 expression limits viral replication in megakaryocytes and prevents infection in surrounding stem cells, indicating that these transcriptional and translational changes in megakaryocytes can be beneficial to the host." (PMID 36194487, 2022). "Furthermore, we note that infection by alpha is enhanced in the presence of IFITM3, and this is abolished by cyclosporine H, cytoplasmic tail deletion, and the H681P mutation." (PMID 36350154, 2022). "Moreover, it has been demonstrated that increasing the amount of IFITM3 protein in IFITM2/3 knockout cells reduces the infection of cells with the influenza virus, depending on the level of the added IFITM3 protein." (PMID 35216030, 2022). "In accordance, blocking Tlr7 and Tlr9 signalling significantly reduced IL-6 in both wt and Ifitm3−/− cells to similar levels following infection with MCMV, suggesting that Ifitm3-mediated regulation of these responses restricts MCMV-induced cytokine production." (PMID 36075894, 2022). "Interestingly, upregulation of antiviral immune genes e.g. interferon-induced transmembrane protein 3 (IFITM3) in megakaryocytes in response to Dengue infection prevents infection of neighbouring megakaryocytes." (PMID 35419008, 2022). "It has been demonstrated that IFITM3 restricts the infection of a variety of viruses in vitro, such as influenza A virus (IAV), Ebola virus (EBOV), Marburg virus (MAVR), SARS coronavirus (SARS–CoV), human immunodeficiency virus (HIV–1), Dengue virus (DENV) and Zika virus (ZIKV)." (PMID 36366505, 2022). "IFITM3 overexpression diminished SARS-CoV-2 S-mediated infection by 2-fold." (PMID 36423162, 2022). "Infection studies with IFITM3-CARC cholesterol binding mutants suggest IFITM3-cholesterol interaction might play an important role in blocking virus entry into host cells mediated by the IAV and SARS-CoV-2 spike glycoproteins." (PMID 34981045, 2021). "Individuals lacking IFITM3 are highly susceptible to infection, even when challenged with influenza virus of low pathogenicity." (PMID 34818332, 2021). "Thus, IFITM3 also promotes systemic infection of Lm in mice by suppressing immune cell recruitment and pro-inflammatory cytokine signaling." (PMID 34404769, 2021). "Furthermore, different multiplicity of infection (MOI) levels affected the ability of exosomes to load IFITM3, reaching the highest loading capacity with an MOI of 100 (number of bacteria: number of cells = 100:1)." (PMID 33816587, 2021). "Consistent with this, liver sections from IFITM3 KO mice revealed a decrease in total number of infection foci per square mm of liver tissue, as well as a decrease in the number of infected cells per infection focus, compared to WT mice." (PMID 34404769, 2021).
infection (continued). "Interestingly, infection studies in A549 cell lines shows IFITM3 has greater antiviral activity against IAV and SARS-CoV-2 infection, whereas IFITM2 is more active against EBOV, that enter host cells through interactions with NPC1 in late endosomes." (PMID 34981045, 2021). "IFITM3 has been described to prevent in vitro infections with some subtypes of hMPV." (PMID 33809875, 2021). "MLV-LP infection was slightly increased by overexpression of IFITM3 in 293T cells." (PMID 34933450, 2021). "Following infection with both low and highly pathogenic avian influenza (LPAI/HPAI) strains, duck IFITM1/2/3 are highly upregulated in the lungs and the ileum from day 1 post-infection, whereas only IFITM3 was modestly upregulated in the ileum of chickens." (PMID 33810083, 2021). "Indeed, infection of Ifitm3−/− mice with different strains of IAV leads to a fulminant viral pneumonia and to death." (PMID 33810083, 2021). "After infection with Brucella M5 at different time points, Western blot analysis showed that Brucella M5 infection could induce the activation of IFITM3 in a time-dependent manner, reaching the highest value at 24 h." (PMID 33816587, 2021). "IFITM3 may also play an important role in virus replication and proliferation after initial infection." (PMID 33766078, 2021). "We also examined whether the time of infection or assay read-out impacted the results in our IFITM3 knockout cells by examining E-protein staining at 24 h post-infection." (PMID 32370187, 2020). "Our study is a proof of concept that new molecules recognized or regulated by the SARS-CoV-2, specifically TMPRSS2 and IFITM3 may be related to infection and anti-viral effect, respectively." (PMID 33061814, 2020). "We previously found that IFITM3 can suppress H5N1 replication in the early stage of the infection." (PMID 33329509, 2020). "The autocrine effects of IFN include changes of cell membrane composition, with increased content of 25-hydroxycholesterol and expression of a set of antiviral genes, such as Interferon Induced Transmembrane Protein 3 (IFITM3) that reduce further cell infection by viral particles." (PMID 32423059, 2020). "To determine whether IFITM3 could restrain PRRSV intercellular spread during infection, we performed a dynamic analysis of PRRSV spread using a coculture system." (PMID 32999030, 2020). "Virions in the presence of IFITM3 resulted in the infection of fewer target cells overall compared with virions in the absence of IFITM3, and a more potent inhibition was observed when both virions and target cells contained IFITM3." (PMID 32999030, 2020). "Interestingly, while IFITM proteins inhibit the entry of all the other human CoVs, HCoV-OC43 hijacks human IFITM2 or IFITM3 as entry factors to facilitate its infection of host cells." (PMID 32641482, 2020). "For example, mutations within the 20YXXΦ23 motif (endocytic signal) that targets IFITM3 to endosomes led to its accumulation at the plasma membrane and restored infection by viruses that enter cells by endocytosis, such as IAV or human coronaviruses NL63 and 229E." (PMID 32485916, 2020). "However, the overexpression of IFITM1, IFITM2, and IFITM3 is unable to inhibit the infection of human papillomavirus (HPV), human cytomegalovirus (HCMV), and adenovirus type 5 (Ad5) although type I IFNs can efficiently reduce HPV infection." (PMID 31156602, 2019). "Notably, we confirmed that the enhanced basal expression level of IFN-α/β was accompanied by moderately increased MX1and IFITM3 mRNA levels, suggesting weak alert of the cellular immune system prior to infection." (PMID 30866762, 2019). "Thus, both ducks and chickens possess functional IFITM3 proteins that block influenza virus entry into cells, but ducks seem able to induce it earlier in infection, possibly thanks to RIG-I signaling." (PMID 30634569, 2019). "IFITM2 and IFITM3 impede viral membrane fusion with endosomes to restrict RVFV infection." (PMID 31156602, 2019).
infection (continued). "The IFITM3 clustering on apparently vesicular structures started early after infection (3–5 h p.i.), with an initial co-localization of IFITM3 with an early endosomal marker and a later co-localization with a late endosomal marker, reflecting the early to late endosomal pathway of IAV." (PMID 31212878, 2019). "Knockout of IFITM3 in mice increased mortality of the animals upon subcutaneous infection with WNV." (PMID 31156602, 2019). "However, the co-localization of IFITM3 and Rab11 was already present in the uninfected A549 cells, with no significant change of co-localization during the course of infection, as shown by the MCC analysis." (PMID 31212878, 2019). "An abortive and ineffective infection might trigger the IFITM3 activation and recruitment to endosomes in the same way as can be seen for an efficient IAV infection." (PMID 31212878, 2019). "It was demonstrated that an IFITM3 knockdown in A549 cells increases infection rates." (PMID 31212878, 2019). "In addition to the role of IFITM3 in the innate immune response, it also protects lung dendritic cells from productive infection with influenza virus, thus allowing their trafficking to draining lymph nodes and priming of CD8 T cells." (PMID 30662816, 2018). "To verify this speculation, we first tested the impact of IFITM3 on the initial phase of infection by incubating BHK-IFITM3 with VTT (5 PFU/cell) on ice for 1 h to permit viral binding but with preventing viral entry into the cells." (PMID 29503647, 2018). "Notably, IFITM3 protein plays an important role in controlling the infection and pathogenesis of IAV, WNV, and multiple alphaviruses in vivo." (PMID 29503647, 2018). "Similarly, IFITM3 KO mice experienced increased lethality upon footpad infection with Venezuelan equine encephalitis virus that was accompanied by increased virus titers in the spleen, liver, spinal cord, and, most significantly, brain [41•]." (PMID 30662816, 2018). "Together, these results showed that IFITM3 expression could inhibit the initial infection and the efficiency of restriction was cell type dependent." (PMID 29503647, 2018). "However, infection by either Vesicular Stomatitis Virus (VSV) or Influenza A Virus (IAV) triggers methylation of IFITM3 by promoting its disassociation from LSD1." (PMID 29281729, 2017). "Finally, the effects played by IFITM3 in the production of infectious virions was assessed by harvesting cell free supernatants at late time points during spreading infections." (PMID 28957419, 2017). "Here, we used the murine CMV (MCMV) model of infection to determine that IFITM3 limits herpesvirus-associated pathogenesis without directly preventing virus replication." (PMID 28240600, 2017). "Furthermore, 14 days after infection with standard inoculum, viral persistence in the salivary gland was evident in WT and Ifitm3–/– mice, but Ifitm3–/– mice harbored an elevated viral load in this established site of persistent MCMV replication." (PMID 28240600, 2017). "However, IFITM3 is more proficient than IFITM1 at preventing infection by the late endosomal- or lysosomal-entering viruses, including IAV and DENV." (PMID 28386554, 2017). "The four viruses tested replicated well irrespectively of the presence of IFITM3 and when virion particles produced during spreading infection were isolated, normalized and analyzed for their infectivity on a single cycle of infection basis, no defects were observed." (PMID 28957419, 2017). "Genes like B2m, Mst1, Igsf1, Ifitm3 and Nt5c2 were found to be upregulated whereas genes like Fyb, Ilf3, Wnt4 and Socs3 were found to be downregulated in the brain against both V3000 and V3034 infections." (PMID 28446152, 2017). "On the other hand, as TCP strongly inhibits IFITM3-mediated antiviral activity by targeting LSD1, it could be potentially applied as an adjuvant to increase RNA virus propagation in IFITM3-competent system so as to assist vaccine industry or infection models." (PMID 29281729, 2017).
infection (continued). "MCMV entry was unaffected by IFITM3 deficiency when cells were infected at an MOI that resulted in nonsaturating infection in WT cells (MOI of 0.1 or 1) or following infection with a higher MOI (MOI = 10)." (PMID 28240600, 2017). "Furthermore, an IFITM3 mutant (Y20A) that is localized to the plasma membrane inhibited infection by cell surface fusion more potently than IFITM1." (PMID 27219333, 2016). "However, viral sensitivity to IFITMs, particularly IFITM2 and IFITM3, increases over the first 6 months of infection, primarily as a result of neutralizing antibody escape mutations." (PMID 27640936, 2016). "Furthermore, when IFITM3 is relocated to the plasma membrane (IFITM3‐Y20A) greater inhibition of infection was seen compared to IFITM1." (PMID 27219333, 2016). "Endocytic infection was low in all IFITM3‐HA cells, with OS‐IFITM3‐HA being the most restrictive." (PMID 27219333, 2016). "In addition, we find that HTNV infection downregulated lncRNA NRIR 48 h post infection, which negatively regulates the transcription of IFITM3." (PMID 28096800, 2016). "Novel PPIs of IFITM1 and IFITM3 shed light on possible mechanisms of host invasion adopted by Zika virus including suppression of the immune system and cognitive and birth defects following infection." (PMID 29333229, 2016). "This may be explained by the fact that IFITM3 is present at low levels within most cells at steady state and is induced by IFNs only after infection has already been established." (PMID 26263374, 2015). "Importantly, knockdown of IFITM3 in both NEDD4 WT and KO MEFs resulted in an increase in influenza virus susceptibility, and largely eliminated the resistance of NEDD4 KO cells to infection." (PMID 26263374, 2015). "However, Ifitm3 is capable of restricting respiratory syncytial virus (RSV) in vivo either through directly restricting RSV cell infection, or by exerting a previously uncharacterised function controlling disease pathogenesis." (PMID 24278312, 2013). "Weight loss profiles showed that neither wild type nor Ifitm3-/- mice had any overt signs of illness over the course of infection." (PMID 24278312, 2013). "Furthermore, we show that chicken IFITM3 is functional in chicken cells and that knockdown of constitutive expression in chicken fibroblasts results in enhanced infection by influenza A virus." (PMID 24067955, 2013). "Cellular infiltrate was quantified over the course of infection, which showed a significant increase in total cells resident in the lungs on day seven pi in Ifitm3-/- mice (p < 0.05) and a similarly significant increase in total cellular infiltrate in the BAL fluid on day four pi (p < 0.01)." (PMID 24278312, 2013). "However, combined knockdown of both IFITM1 and IFITM3 led to even greater infection." (PMID 42262132, 2026). "The quick action of neutralizing antibodies or memory T cells may render IFITM3 non-essential in the early control of infection, thus explaining the lack of consistent associations between IFITM3 SNPs and severe outcomes in seasonal influenza." (PMID 40237465, 2025). "However, it remains unclear whether IFITM3 KO mice experience altered antibody responses following natural infection or vaccination via the more clinically relevant intramuscular route." (PMID 40501891, 2025). "However, some studies do not find a consistent link between IFITM3 SNPs and infection severity, causing uncertainty about its role in vivo." (PMID 40237465, 2025). "Broad testing of IFITM3 status in the human population could bolster pandemic prevention efforts by allowing vulnerable individuals to receive greater vaccine coverage or exercise enhanced precautions when encountering animal reservoirs of infection." (PMID 39477971, 2024). "The enhanced immune priming in Ifitm3-deficient mice explained improved pathogen clearance in this model, thus providing the first in vivo evidence for the importance of immune regulation by IFITMs in a nonviral infection modality." (PMID 36435199, 2023).
infection (continued). "As a hypothesis, HBV and HDV might hijack IFITM3 in endosomes after successful endocytosis to prevent degradation in an early infection period, whereas in a later phase of infection, the suppression of the host’s IFN response would be beneficial for the completion of the viral replication cycle." (PMID 35458456, 2022). "Besides, stabilization of IFITM3 AH1 by S-palmitoylation of Cys72 may also explain the subcellular distribution of IFITM3 during infection." (PMID 35769480, 2022). "A semi-automated image analysis of IAV A/HK/1/68 (pdmH3N2) and IAV A/R/D6/2009 (pdmH1N1) infected A549 cells revealed IFITM3 clustering early after infection in both cases, with few differences in kinetics, which may reflect strain specific replication kinetics." (PMID 31212878, 2019). "Our results show that IFITM3 expression on effector T cells is crucial for these cells to mediate their effector function and highlights an interferon independent pathway for the induction of IFITM3, which if targeted, could be an approach to harness the activity of IFITM3 for infection prevention." (PMID 30650117, 2019). "Furthermore, the infection was also inhibited by the expression of IFITM3 in BHK-21 and A549 cells." (PMID 29503647, 2018). "Although the actual mechanisms remain unclear, previous studies have demonstrated that IFITM3 protein restricted infection by blocking cytosolic entry of viruses utilizing the endocytosis pathway, and also by affecting viral-endosomal membrane fusion to block viral nucleocapsid release." (PMID 29503647, 2018). "Indeed, disruption of endogenous IFITM1 and IFITM3 by shRNA greatly enhanced ATMUV infection." (PMID 28473814, 2017). "Exacerbated MCMV-induced weight loss in Ifitm3–/– mice was accompanied by a statistically significant higher viral load from day 4 p.i. in the spleen and lungs, but not the liver, after infection with standard inoculum (3 × 104 PFU)." (PMID 28240600, 2017). "In addition to impaired CD8+ T cell responses, the reduction in expression of some ISGs may also contribute to the enhanced pathogenesis, since defective expression of individual antiviral factors, like IFITM3, can alter the course of infection." (PMID 26241898, 2015). "IFITM3 overexpression up-regulated LC3B II/LC3B I, Beclin-1, ATG7, and ATG5, but down-regulated p62 during infection." (PMID 40681213, 2025). "Additionally, whether the small defects reported for antibody responses in IFITM3-deficient humans and mice have functional consequences during challenge infections have not been examined." (PMID 40501891, 2025). "In HEK293T cells stably expressing IFITM3 WT or IFITM3 G95L, which differ with respect to STX7 binding potential, IAV was added to cells at a multiplicity of infection of 1 and incubated on ice for 40 min." (PMID 39653855, 2025). "qRT-PCR results showed that mRNA levels of IFITM3, IFN-α1, and IFN-β were up-regulated in response to 24 h infection of C. parvum." (PMID 40681213, 2025). "TLR7 and IFITM3 are both endosomal proteins that have opposing effects on hMPV infection, with TLR7 promoting infection and IFITM3 restricting it." (PMID 40235933, 2025). "Furthermore, IFITM3-knockdown cells maintained higher infection susceptibility than control cells after treatment with type I interferon, demonstrating that IFITM3 plays a critical and non-redundant role in the human antiviral interferon response against diverse influenza viruses." (PMID 39477971, 2024). "For example, infection of common cold human coronavirus OC43 is promoted by IFITM2 and IFITM3 at the step of virus entry." (PMID 38793616, 2024). "We observed that HSV1 MOI 1.0 infection was able to reduce the APOBECG, Tetherin, and IFITM3 expression in macrophages." (PMID 39476027, 2024). "While IFITMs have widely been demonstrated to inhibit infection, in hCoV, OC43, IFITM2, and IFITM3 have been shown to increase viral entry into cells." (PMID 37985854, 2024).